IL2 (interleukin 2)
Diseases named in the same sentence as IL2 in open-access papers (continued):
Sharing a sentence is not in itself a finding about the gene and the disease.
tumor (continued). "Conventionally, TIL therapy requires large-scale expansion of a small number of T-cells grown out from tumor tissue fragments stimulated with high dose IL-2 and anti-CD3 antibody." (PMID 35222439, 2022). "Usually, the IL-2 dose used in humans corresponds to 600,000 IU/kg, and it is considered a high dose treatment; in most tumor experiments in mice, an equivalent dose of 30,000 IU is used, corresponding with 1–3 μg of wtIL-2 per dose." (PMID 36059465, 2022). "Expansion with IL-15 produces CAR T cells, demonstrating high SRC (metabolic fitness), stemness, persistence, and superior anti-tumor activity when compared to cells expanded with IL-2." (PMID 35645205, 2022). "IL-2 levels of mice in the tumor-bearing group were relatively low compared with those of mice in the normal group; however, this difference was not significantly different." (PMID 35281908, 2022). "As previously documented, TKD/IL-2 activated NK cells can recognize and kill tumor cells expressing mHsp70 within 4 hours of co-incubation." (PMID 35720311, 2022). "During tumor progression, T-cell-mediated antitumor response is significantly impaired, characterized by low secretion of interleukin-2 (IL-2), TNF-α, and interferon-γ (IFN-γ) and a high expression of inhibitory receptors such as PD-1." (PMID 35216168, 2022). "In this study, S. mitis activated signaling of IL-2, an interleukin known to enhance anti-tumor immunity." (PMID 35600164, 2022). "IL-15 is a potent stimulator of CD8+ T cells and NK cells via the activation of IL-15Rα, IL-2Rβ (also named CD122), and IL-2Rγ (also named CD132), which share receptors with IL-2, IL-4, IL-7, IL-9, and IL-21, and thereby reduces tumor burden." (PMID 36439125, 2022). "It was observed that tumor growth in animals treated with wild or mutant IL-2 proteins was significantly inhibited compared to the PBS treated control mice." (PMID 35354847, 2022). "Together, this data suggests that Salmonella + Alb-IL2 is an effective approach to reduce tumor burden compared to single agent treatments." (PMID 35962391, 2022). "We used T cell coculture, flow cytometry, ELISA, CCK8 assay and crystal violet staining to detect the expression of regulatory T cell (Tregs), IFN-γ, IL-2 and the ability of T cell-mediated tumour cell killing respectively." (PMID 35971127, 2022). "Similar results were also found by Xu and colleagues that among CAR T cells expanded with different common γc cytokines, IL-2-exposed CAR T cells exhibited the poorest anti-tumor function." (PMID 35493513, 2022). "After coculture with IL-15 and IL-2 for 7 days, the cell viabilities were measured for each type of tumor based on LDH method." (PMID 36213822, 2022). "Observations revealed that tumor volume of the mutant IL-2-treated mice was significantly decreased in comparison with the wild IL-2 treated group (P < 0.001)." (PMID 35354847, 2022). "An additional qPCR analysis of the tumour cells showed significant increases in Il2, Ifng, Il1b, and Il18, and decreases in Il4, Il5, and Tgfb1, indicative of Th1‐dominant immune response." (PMID 35430766, 2022). "The activation of TGF-β and IL-10 play an immunosuppressive role in the tumor microenvironment, while IL-2 can enhance the immune response of cancer patients." (PMID 36476246, 2022). "Treatment with combination therapy increased the plasma concentrations of IFN-γ, TNF-α, IL-2, and IL-6, indicating that tumor-infiltrating Treg cells gained CD4 effector function." (PMID 36090972, 2022). "To overcome suppression, we engineered circuits in which tumor-specific synNotch receptors locally induce production of the inflammatory cytokine, interleukin-2 (IL-2)." (PMID 36520915, 2022). "Pro-inflammatory mediators such as IL-22, IL-6, IL-2, and IL-17 play a key part in maintaining tumor microenvironment, promoting immunosuppression, angiogenesis, and coordinating the interactions between immune cells." (PMID 36249057, 2022).
tumor (continued). "Some success has been obtained in maintaining immune cell presence in air–liquid interface cultures of tumor tissues for at least the initial few weeks of culture through the use of IL2-mediated stimulation." (PMID 35123116, 2022). "Using a synNotch receptor that detects the tumor to drive IL-2 production provides a simple and modular way to achieve this goal." (PMID 36520915, 2022). "They further evaluate the antitumor immunotherapy effect of PD‐L1 siRNA and IL‐2 pDNA‐loaded TT‐LDCP NPs in orthotopic HCC tumor model." (PMID 35343112, 2022). "M0 macrophages can be stimulated by interferon-γ (IFN-γ) into activated anti-tumor M1 macrophages which exerts cytotoxic effect on tumor by secreting cytokines like IL-2 and TNFα." (PMID 36253762, 2022). "Adoptive cell therapy consists of the isolation of TILs from the excised tumor, expansion of these cells by interleukin-2 (IL-2) treatment and re-infusion into lympho-depleted patients with treatment of IL-2 in addition." (PMID 35053435, 2022). "From 16 patients in our cohort tumor material, i.e., skin metastases, was available before start of IL-2 treatment and under intralesional therapy." (PMID 35158808, 2022). "Recent studies have proven that IL2/STAT5 signaling pathway induces depletion of CD8+T cells in the tumor microenvironment, thereby inhibiting anti-tumor immunity and promoting immune escape of the tumor cells." (PMID 35903691, 2022). "These researchers reported that these CAR-Ts mediated target antigen-dependent IL-2 secretion after stimulation by MUC1-expressing tumor cell lines." (PMID 35468841, 2022). "TGF-β-rich exosome inhibits lymphocyte responses to IL-2, thereby altering the tumor microenvironment to promote immune escape functions of tumor cells." (PMID 35747825, 2022). "The T cell receptor (TCR) on CD8+ T cells binds to the MHC-I compound on tumor cells, resulting in the production of cytolytic factors (e.g., perforin and granzyme) and inflammatory cytokines (e.g., IL-2 and IL-12) that directly kill tumor cells." (PMID 36532066, 2022). "One study evaluated the efficacy of the WT colon tumor cell antigen vaccine used with recombinant mouse GM-CSF and IL-2 as cytokine adjuvants in a BALB/c murine tumor model." (PMID 36275766, 2022). "In TIL-based ACT, naturally infiltrating lymphocytes are isolated from the resected tumor materials and ex vivo expanded in the presence of a high dose interleukin-2 (IL-2) to therapeutic numbers, or approximately 10-100 billion cells." (PMID 36612092, 2022). "Concentration of pro‐inflammatory and pro‐angiogenic cytokines including IL‐1a, IL‐2, IL‐6, IL‐10, IL‐12, and IL‐17A, in peripheral blood of tumor bearing mice receiving anti‐MUC1 nanobody was significantly lower compared to the PBS receiving group." (PMID 34694686, 2022). "IL-2 was also shown to be critical for regulatory T cell function, which promote an immunosuppressive tumor microenvironment." (PMID 35965494, 2022). "In the first phase, lymphocytes were separated from tumor tissues and were cultured in vitro, and then were activated in the medium containing a high concentration of IL-2 to further increase tumor-reactive T cell clones." (PMID 35606862, 2022). "IL-2 was administered s.c. under the xenograft tumor on days 1, 3, 5 and 7 post-therapy-initiation at a dose of 25,000 IU/mouse." (PMID 35836798, 2022). "Since T cells, either unstimulated or stimulated with TKD/IL-2, are unable to recognize mHsp70 on tumor cells, an anti-Hsp70 CAR was transduced into primary T cells." (PMID 35720311, 2022). "In contrast to the in vitro models, eNK cells in combination with IL-2 significantly and similarly delayed tumour growth in both cell lines." (PMID 35747143, 2022). "We tested if adding an IL2 gene to LV-shFDPS and expressing both in a tumor cell line, would increase Vδ2 T cell activity in a coculture assay." (PMID 36275712, 2022).
tumor (continued). "Toxicity from IL-2 treatment arises from on-target, off-tumor activation of systemically circulating immune cells." (PMID 36712341, 2022). "In tumor microenvironment, Tregs express IL-2 receptors with high affinities that surpass the T-effector cells to obtain limited IL-2." (PMID 35371055, 2022). "Targeting IL-2 further reduces the levels of CD8+ effector cells in the tumor microenvironment and, in fact, IL-2 injections have been found to increase survival in human trials." (PMID 36428581, 2022). "The Treg cells are ubiquitous in TIME and promote the development and progression of the tumor by suppressing the anti-tumor immune responses, such as the secretion of interleukin-2 (IL-2)." (PMID 36428805, 2022). "The spleen index and serum levels of TNF-α, IFN-γ, and IL-2 in B16F10 tumor metastasis mice treated with Nr-CWS were significantly increased." (PMID 36110249, 2022). "Tumor infiltrating lymphocytes (TIL) are harvested immune cells that are selected based on their ability to recognize tumor cells, expanded, and then infused back into the patient with a T cell activating cytokine (IL-2)." (PMID 36430440, 2022). "Inflammatory cytokines within the tumor microenvironment, such as interleukin (IL)-2, IL-6, IL-10, IFNs and tumor necrosis factor α, have also been shown to induce B7-H4 expression on both tumor cells and monocytes/macrophages." (PMID 34275008, 2022). "NK cells activated by IL-2 which combined with anti–PD-1 can inhibit tumor growth in xenograft GC models." (PMID 36225938, 2022). "Enhanced glycolysis metabolism in primed CD8+T cells promotes their secretion of IFN-γ and IL-2 which accentuates their anti-tumor function." (PMID 36003368, 2022). "Subsequent increases in IL-2 and IL-6 in tumor biopsies after infusion further demonstrated pro-inflammatory liver TME." (PMID 36238297, 2022). "To study the effects of local IL-2 production within fully immunocompetent mouse tumor models, we rebuilt our synthetic IL-2 circuit in primary mouse T cells." (PMID 36520915, 2022). "As expected from the previous studies that described the anti-tumor effect of these conditioning regimens, both TBI and IL-2 treatments improved the anti-tumor activity and survival rate of Pmel-1-infused mice." (PMID 36497152, 2022). "The recombinant virus produced high levels of human IL2 in infected tumor cells and suppressed tumor cell growth efficiently, maintaining its replication in vitro." (PMID 35799600, 2022). "Meanwhile, lymphocyte has the role of secreting interleukin (IL)-2, which inhibits tumour cell proliferation by activating and stimulating the proliferation of cytotoxic lymphocytes." (PMID 36614896, 2022). "Since i.t. administration inherently increases drug exposure at the tumor, we reduced the IL-2 dose from 1 to 0.4 nmol, and the frequency of IL-2 dosing from thrice weekly to twice weekly." (PMID 36712341, 2022). "IL-2WT appears to have a stronger tumor-suppressive effect than IL-2K35C-moFA, possibly because IL-2K35C-moFA has fewer IL-2 molecules at the same dose." (PMID 36230665, 2022). "Early clinical studies of the therapeutic potential of stimulating T cells in cancer patients evidenced that administration of interleukin-2 (IL-2) can lead to durable tumor regressions in advanced cancers." (PMID 35720306, 2022). "Strategies to improve IL-2 therapy depend on preferentially increasing tumor exposure while decreasing systemic exposure." (PMID 36712341, 2022). "Subsequent administration of Alb-IL2 will support the expansion and effector function of tumor-specific T cells." (PMID 35962391, 2022). "Our study also revealed a new target for tumor-specific T cells and the novel function of IL-2 in reactivating PD-1+TIM3+ T cells." (PMID 35104810, 2022). "Several recent approaches have been taken to target IL-2 and other cytokines to specific locations, such as the tumor microenvironment." (PMID 36261022, 2022).
tumor (continued). "Because of IL-2 induction and enhancement of cytotoxic activity, it was used extensively in clinical research and tumor treatment." (PMID 35082324, 2022). "T cells survival in tumor tissue is vital to sustain an anti-tumor response, which relies on the interleukin 15 pathway and interleukin 2 pathway." (PMID 35264912, 2022). "Directly targeting T cells to the tumour with anti-GD2 mAb conjugated to IL-2 improved the response of endogenous T cells and NK cells." (PMID 35205725, 2022). "Overall, our data demonstrate that our next-generation PD-1–laIL-2 construct can carry the T cell growth factor IL-2 to tumor-specific T cells in a safe and effective manner." (PMID 35104810, 2022). "By contrast, treatment with EGFR CAR T cells led to an upregulation of the adhesion molecule CD54 on tumor cells, with further augmentation upon IL-2 administration." (PMID 35836798, 2022). "Vδ2 T cells activated with TGF-β have also shown to have better yield, viability, cytokine release and tumor cell killing compared to IL-2 activated controls." (PMID 36429001, 2022). "In this case, IL-2 was labelled with fluorine-18 via reaction with succinimidyl 4-[18F]-fluorobenzoate ([18F]SFB) to monitor tumorreactive T cells directly at the tumor site." (PMID 35099641, 2022). "Previously, we demonstrated in mice that large antibody–IL-2 fusions have compromised tumor-targeting due to their prolonged circulation and uptake by abundant IL-2-receptor-expressing cells in the blood." (PMID 36712341, 2022). "Whereas, when irradiated tumor cells were mixed with the activated mouse splenocytes, production of IL-2 and IFN-γ was blocked." (PMID 36229853, 2022). "Th2 cells, which primarily secrete IL-2 and IL-10, have been shown to promote immunosuppression, and tumor progression and metastasis." (PMID 36276933, 2022). "When comparing skin metastases in this patient from baseline to being under IL-2 treatment, a marked increase of tumor infiltrating CD4+, CD8+ and PD-1+ T cells is seen." (PMID 35158808, 2022). "As expected, the immunotherapy with DB showed, in the resistant tumor model, similar tumor growth compared to the monotherapy controls with FAP-IL-2 or IL-2." (PMID 36230765, 2022). "These cells are then infused into patients with high-dose IL-2 to support the growth and survival of infused cells in the tumor microenvironment." (PMID 36612092, 2022). "For these reasons, IL-2 has been widely implemented as a strategy to enhance anti-tumor T cell responses." (PMID 35962391, 2022). "The influence of intralesional treatment with interleukin-2 (IL-2) on the clinical course and tumour progression of canine TCC was evaluated in a retrospective clinical study." (PMID 35324835, 2022). "Upon intravenous delivery into immunocompetent mice, such immunocytokines led to similar tumor growth delay as size-matched untargeted IL-2." (PMID 36712341, 2022). "Here, we engineer small interleukin-2 (IL-2) immunocytokines fused to nanobodies with nanomolar to picomolar affinities for the tumor-specific EIIIB domain of fibronectin (also known as EDB)." (PMID 36712341, 2022). "Later, scholars noted that low dose of IL-2 can enhance the cytotoxicity of immunocyte and the efficacy of anti-tumor drugs, including hRS7, hI-con1, herceptin, adecatumumab, trastuzumab and pertuzumab in USPC patients." (PMID 36531027, 2022). "Peritoneal lavage with oxidized liquids moreover increased lymphocyte infiltration into the tumor nodules, accompanied by considerable increases in intratumoral IL2 in the conducting group." (PMID 35892641, 2022). "designed ChPD1-T cells for recognizing and damaging tumor cells by secreting inflammatory factors such as IL2, IL-17, IL-21, IFN γ, TNF, and GM-CSF and decreasing the inflammatory suppressor cytokine IL-10." (PMID 35935930, 2022). "TIL can function as any normal T cell by lysing tumor cells and/or secreting IL-2, IFN-γ, and other cytokines when stimulated by tumor cells." (PMID 35335089, 2022).
tumor (continued). "The CD16A can also enhance the interleukin-2 (IL-2) and interleukin-15 (IL-15)-driven NK cell proliferation and cytotoxicity against tumor cells." (PMID 36359863, 2022). "This is significant as in our study, we observed that additional IL-2 supply at the tumor site led to a drastic upregulation of PD-1 expression and induced a tendency towards an exhaustive T cell state." (PMID 35836798, 2022). "Some studies suggest cutting tumor mass into 1 mm3 pieces and putting them into cell-culture media containing high-dose interleukin-2 (IL-2) for two weeks." (PMID 36389779, 2022). "Taken together, we observed the effect of TBI and IL-2 treatments on immune cell populations in lymphoid and tumor tissues." (PMID 36497152, 2022). "Further, a significant increase in IFN-γ+IL-2+ double cytokine production by both tumor-infiltrating CD8+and CD4+ was obtained in the Lm-LLO-CD105A treated group in comparison to the Control Lm treated group." (PMID 36439126, 2022). "Accordingly, anti-PD1 and IL-2 potentiated anti-tumor responses in TransCon TLR7/8 Agonist treated tumors." (PMID 36123697, 2022). "Increasing IL-2 accumulation in the TME via fusion of IL-2 with tumor-targeting molecules is another way to explicitly promote CD8+ T-cell proliferation and reduce toxic side effects." (PMID 35410257, 2022). "It reported that IL-2 on Tregs regulates the effector CD8+ T cells, and the loss of IL-2 would partly explain the exhausted phenotype occurring during tumor responses." (PMID 35585567, 2022). "Next, we evaluated the capacity of the IL-2 mutein to change the balance of CD8+MP/Tregs in tumor-bearing mice." (PMID 36059465, 2022). "Although several cytokines [such as interleukin (IL)-21, IL-15, and IL-2] are well known as NK cell activators, IL-2 is majorly used in clinical trials to increase the anti-tumor potential of NK cells." (PMID 36059847, 2022). "LKLF (or KLF2) is a zinc finger-containing transcription factor that plays a negative regulatory role in cytotoxic T-lymphocyte (CTL), killing tumor cells by blocking the mimicry of IL2, tumor necrosis factor (TNF)-α, and interferon (IFN)-γ." (PMID 36341370, 2022). "To further dissect the contribution of IL2 to anti-HER2 mAbs-induced ADCC, we took advantage of our HER2+ 3DiBC preclinical tumor model that we treated with trastuzumab and recombinant human (rh) IL2." (PMID 36085201, 2022). "Synthetic circuits that deliver IL-2 locally to tumors allow CAR-T cells to overcome suppressive tumor microenvironments." (PMID 36520915, 2022). "Using the recently developed synthetic Notch (synNotch) receptor, we have created a bypass signaling pathway in which tumor recognition by synNotch induces local interleukin-2 (IL-2) production." (PMID 36520915, 2022). "In vivo potency was increased by transducing tumor cells with a vector expressing both shFDPS and human IL-2." (PMID 36275712, 2022). "Naïve mouse splenocytes produced minimal amount of IFN-γ and IL-2 when co-cultured with unirradiated tumor cells." (PMID 36229853, 2022). "Our results showed that when combined with BiTE, T cells carrying CD3εζ28 had better killing effects on tumor cells and expressed higher levels of IL-2 and IFN-γ and the genes related to T cell activation than normal T cells." (PMID 36230871, 2022). "Pro-inflammatory cytokine production including tumor necrosis factor α (TNFα), IFNγ, and IL-2 were significantly elevated in tumor-infiltrating CD8 + T cells from Salmonella + Alb-IL2 treated mice compared to mice treated with Salmonella or Alb-IL2 alone." (PMID 35962391, 2022).